TLR1 (toll like receptor 1)
Diseases named in the same sentence as TLR1 in open-access papers (continued):
Sharing a sentence is not in itself a finding about the gene and the disease.
Td (1 paper, 2016). "In all subjects combined, 2 SNPs in TLR1 were significantly associated with Td, and one SNP in TLR2 was significantly associated with BOP." (PMID 27727278, 2016). "In all subjects combined, 2 SNPs in TLR1 (−2192T>C, 1805G>T) were significantly associated with Td, and one SNP in TLR2 (597T>C) was significantly associated with BOP." (PMID 27727278, 2016). "Thus, our finding that TLR1 −2192C, −7202A, and 1805G alleles are significantly associated with Td is noteworthy, and may be considered as a starting point in identifying the contribution of TLR1 variation to PD." (PMID 27727278, 2016).
temporal lobe epilepsy (1 paper, 2024). A localization-related (focal) form of epilepsy characterized by recurrent seizures that arise from foci within the temporal lobe, most commonly from its mesial aspect. "Toll-like receptor 1 (TLR1) was also shown to be predictive of seizure frequency in our study and is implicated in temporal lobe epilepsy as a key transduction receptor of neuro- inflammation-induced epileptogenesis through glial production of inflammatory cytokines, IL-1β and TNF-α." (PMID 38166692, 2024).
vulvovaginal candidiasis (1 paper, 2014). Infection of the vulva and vagina with a fungus of the genus CANDIDA. "Genetic association of recurrent vulvovaginal candidiasis (RVVC) with polymorphisms in DECTIN-1, CARD9, TLR1, TLR2, and TLR4 genes." (PMID 25295030, 2014).
infection (107 papers, 2009 to 2026). The state of being infected such as from the introduction of a foreign agent such as serum, vaccine, antigenic substance or organism. "The absence of TLR1 expression during an acute infection causes chronic immune activation and the transmutation of microbiota." (PMID 37446274, 2023). "A study performed in African American women, (TLR1) rs5743618TT was associated with CT infection and women with PID who had rs1927911 CC (TLR4) and had high chances of contracting the CT infection." (PMID 37937275, 2023). "The mRNA expression levels of the genes encoding TLR1-10 in PEDV infected NECs were determined by RT-PCR at various timepoints following infection." (PMID 33597007, 2021). "The presence of the allele TLR1*aa10 decreased the risk of infection with the nematode A. tetraptera by 5-fold, yet this effect was insignificant after correcting for multiple comparisons." (PMID 29849060, 2018). "A functional I602S SNP in TLR1 can regulate the innate immune response to lipopeptides caused by a pathogen infection, which could potentially affect inflammatory pathways, although there is no study about this allele in the Japanese population." (PMID 40310362, 2025). "Several of these receptors, including toll-like receptor (TLR)-1, 2, 4 and 9, have been associated with host susceptibility/resistance to paratuberculosis in cattle, but there are fewer studies about their expression at the infection site." (PMID 40646740, 2025). "Importantly, an association between specific TLR1 alleles and infection with the blood pathogen Bartonella has also been identified." (PMID 36699132, 2023). "For instance, the production of tumor necrosis factor (TNF) α and interleukin-6 (IL-6), after TLR1/2 engagement, was down-regulated in older adults, compared with younger populations, suggesting that diminished TLR1/2 signaling contributes to an increased risk of infection in older adults." (PMID 36808423, 2023). "One group reported that defects in TLR1/2 may result in a higher risk of infection and weak vaccine response." (PMID 23391127, 2013). "Excessive inflammation observed with TLR1-1805GG alleles could result from a failure of immune tolerance to continued stimulation with B. burgdorferi which may occur during the course of natural infection." (PMID 41333458, 2025). "In humans, a non-synonymous TLR1 SNP located within the transmembrane domain, which had an impact on TLR1 trafficking, NFκB activity and cytokine output, was found to have strong associations with susceptibility to and progression of infection by Gram positive bacteria and Mycobacterium leprae." (PMID 22417166, 2012). "Activation of platelet TLR1/2 at the initiation of Leishmania major infection results in the release of the Wnt antagonist Dickkopf-1 (DKK1)." (PMID 41858624, 2026). "The anticoagulant PROC associated positively with TLR1 and TLR9, but, with infection, became inversely correlated with TLR2, TLR5, and TLR8." (PMID 40825056, 2025). "Our in silico data suggest that F14 plays a crucial role in mediating the pathogenesis of Mpox infection by acting as a ligand for cell-surface TLR1/2, thereby eliciting inflammatory signals during the infection." (PMID 40165949, 2025). "Contrary to the observed in the liver, tlr1 expression levels in the head-kidney increased post-infection and were higher in naïve fish compared to vaccinated fish." (PMID 41256851, 2025). "We quantified the expressions of TLR1-13 in the cerebellum during the pathogenesis of 22L strain-infected mice and control mice at various time points (60, 90, 120, and 145 days post-infection)." (PMID 38698886, 2024). "Our further data demonstrated that the transcription levels of TLR1 increased significantly after the infection of exogenous A. hydrophila when compared with the control group, revealing that TLR1 participated in bacterial infection in hybrid yellow catfish." (PMID 37056759, 2023).
infection (continued). "Meanwhile, our research provides a reference dataset for in-depth studies on the molecular mechanisms of (TLR1-2) - MyD88 - FADD - Caspase 8 mediating apoptosis pathway in bony fish after the bacterial pathogen infection." (PMID 37056759, 2023). "Salmon head kidney cells (SHK-1) respond to an infection with P. salmonis through the overexpression of tlr1 and tlr5s." (PMID 36899738, 2023). "TLR2, in conjunction with TLR1, plays an important role in the innate immune response by recognizing microbial lipoproteins and lipopeptides in the process of infection." (PMID 37056759, 2023). "Using molecular marker expressivity and post-mock infection cytokine dynamics as baselines, this analysis revealed that patients in Cluster 3 had maximal expressions of NP and TLR1–3 within macrophages." (PMID 37900310, 2023). "Upon infection with H. pylori J99 strain, we noted that TLR1, TLR2, and TLR6 mRNA transcripts were merely upregulated by approximately 2-fold." (PMID 36317079, 2022). "Among TLRs that can recognize the PAMPs, only TLR1/2 is upregulated in 5-ASKH infection compared with FV9, suggesting its possible contribution to this phenotype." (PMID 36190414, 2022). "In THP-1 cells, S. flexneri also stimulated IL-8 production but did so by activating the TLR1/2 signaling pathway, and infection induced rapid THP-1 cell death." (PMID 34933448, 2021). "The transcripts of Tlr1, Tlr5, Tlr11, and Nod2, Nlrp1a, Naip2, and Nlrc4 were significantly higher in the Nlrp3−/− than wild-type mice on day 7 post-infection." (PMID 34690967, 2021). "Here, we found a significant effect of TLR1 and TLR5 alleles on the risk of infection with Bartonella sp." (PMID 29849060, 2018). "Tlr1 was the only other up-regulated cell-surface receptor and was more strongly expressed later during infection." (PMID 26367386, 2015). "Consistent with previous reports, B. thailandensis upregulated expression of TLR1 and TLR2 by two h post-infection, and increases in TLR1, TLR2, TLR3, TLR4, and TLR5 mRNA expression were observed by eight h post-infection." (PMID 23675544, 2013). "Simultaneous inhibition of CD86 and MHCII by TLR1/2 activation would impart a major hindrance on recruitment of adaptive help at the site of infection." (PMID 22529866, 2012). "In Sf9 cells infected with DSP-PP240 virus, tlr1 mRNA expression was highest at 1 day post-infection but dropped dramatically from day 2 to day 4 post-infection." (PMID 22815932, 2012). "Regarding bacterial recognition receptors, tlr1, which recognizes bacterial lipoproteins, showed decreased expression following infection, whereas tlr5, responsible for detecting bacterial flagellin, increased, peaking at 24 hpi before returning to baseline levels by 48 hpi." (PMID 41256851, 2025). "The findings help explain how early events during the infection may contribute to sustained immune activation after antibiotics and point to the role of TLR1 signaling in immune regulation." (PMID 41333458, 2025). "After infection with A. hydrophila, the transcriptional levels of TLR1, TLR2, caspase 8, MyD88, FADD, TOLLIP isoform 1 and TOLLIP isoform 2 were all significantly up-regulated in the kidney, indicating that bacterial infection induced the activation of TLR signaling pathway in the yellow catfish." (PMID 37056759, 2023). "tlr18 is a fish-specific toll-like receptor expressed in the skin, regulated by infection challenge and lipopolysaccharides, and may be homologous to the mammalian tlr1 which binds lipopeptides." (PMID 37228511, 2023). "The expression profiling of TLR signaling pathway genes after pathogen stimulation showed that the infection of pathogens induced the activation of (TLR1-2) - MyD88 - FADD - Caspase 8 involved signaling pathway, and inhibits the spread of bacteria in the body through cell apoptosis." (PMID 37056759, 2023). "Our data suggest that impaired TLR1/2 signaling in MyD88−/− mice may have contributed to this phenotype observed during 5-ASKH infection." (PMID 36190414, 2022).
infection (continued). "Therefore, we thought that the TLR1/2 signaling pathway would contribute mainly to the enhanced inflammatory response in 5-ASKH infection." (PMID 36190414, 2022). "By contrast, the expression of TLR1 increased significantly after infection, indicating that it may be involved in initiating the cellular immune responses of organoids to T. rubrum infections." (PMID 33414472, 2021). "Similarly, stable TZMbl-T10 cells transiently over-expressing TLR2 or TLR1 also enhanced proviral pol DNA at 8 h post-infection compared with the empty vector-transient stable cells (P < 0.05)." (PMID 30930906, 2019). "To gain biological insights into the dynamics of human infection, we recruited a cohort of four individuals bearing the wild-type TLR10 allele (WT) and four individuals bearing a polymorphism in the TLR1/6/10 locus (TLR10 N241H (rs11096957), henceforth termed TLR10)." (PMID 31332193, 2019). "In humans, polymorphism in TLRs (TLR1, NOD2, TLR6 and TLR10) might be associated with the reduced production of cytokines after infection and finally less responsiveness of macrophages to infection." (PMID 29321921, 2018). "This has been shown in mice (Myd88-/- and Tlr2-/- mice have significant immune and host defense defects) as well as in humans (TLR2 expression and a Tlr1 polymorphism are associated with altered immune response to B. burgdorferi OspA vaccination and B. burgdorferi RST1 infection, respectively)." (PMID 26252010, 2015). "In contrast to the response in the immune cells, the expression of TLR15 was the highest after 24 h of infection (11-fold, p < 0.001), whereas TLR1 and TLR2 expression remained unchanged or was even slightly down-regulated, correlating to the results observed in chicken macrophages." (PMID 24134665, 2013). "Furthermore, as observed upon treatment with purified VCC, V. cholerae-induced cytokine production was also attenuated upon infection in the neutrophils, isolated from the TLR1-/-, MyD88-/- and C3H/HeJ (TLR4-defective), mice as compared to those from the wild type mice." (PMID 40184418, 2025). "Thus, further studies are required to assess if an impaired TLR1 response facilitates reduced resistance to microbial pathogens, which may lead to future infection, chronic inflammation or PD pathology in the long term." (PMID 33328979, 2020). "One of the factors that could modify H. pylori infection is genetic predisposition; single nucleotide polymorphisms (SNPs) in TLR genes, such as TLR1, TLR2, TLR4 and TLR10, were shown to alter the bacterial binding, thereby modulating the risk of infection and subsequent cancer." (PMID 30641993, 2019). "Moreover, the decline in expression of tlr1 mRNA after infection, which may be due to baculovirus inhibition of the endogenous gene expression, paralleled the decline seen in DSP-PP240 cleavage activity in the conditioned medium." (PMID 22815932, 2012). "In this study, we have demonstrated that DKK1 produced via the TLR1/2-MyD88 dependent pathway elevates LPA and NPA formation, as well as the infiltration of activated neutrophils into the infection site of BALB/c-infected mice." (PMID 40502169, 2025). "In contrast, TLR1, TLR3 and TLR5, expression was significantly downregulated, whereas TLR6 remained unchanged throughout the infection period." (PMID 41305370, 2025). "Further observations also found that while both rKaSPI and rAdSPI promoted TLR-4 expression, T. spiralis infection also involves the regulation of TLR-1 and TLR-2 expression, highlighting the complexity of the parasite’s infection mechanism." (PMID 39799330, 2025). "In particular, genes that are known to activate NF-kappaB, e.g., TLR1, TLR3, TRAF5 and CD14, showed increased expression over infection time." (PMID 36544767, 2022). "It showed upregulation of multiple inflammatory transcripts, including Toll-like receptor 1/2 (TLR1/2), CD69, and CARD14, upon 5-ASKH infection." (PMID 36190414, 2022).
infection (continued). "SS1 strain infection induced TLR6 mRNA transcript up to 8.2-fold (P < 0.0001); however, the changes in expression levels of TLR1 and TLR2 were either insignificant or scarcely downregulated." (PMID 36317079, 2022). "We generate 977 miRNA-sequencing profiles from primary monocytes from individuals of African and European ancestry following activation of three TLR pathways (TLR4, TLR1/2, and TLR7/8) or infection with influenza A virus." (PMID 32731901, 2020). "In response to TLR1/2 (PamCys2) or TLR4 (LPS) stimulation, monocytes produced a strong TNF and moderate IL‐12 response, which increased at peak infection." (PMID 32566226, 2020). "First, we show that activation of major innate immunity pathways, such as TLR1/2, TLR4 and TLR7/8, and infection with a live strain of IAV increase isoform diversity and elicit a marked remodelling of the isoform repertoire." (PMID 30975994, 2019). "In vivo experiments in chickens further confirmed the observed inflammatory and innate responses induced by vvIBDV in DT40 cells in vitro, and IL-1β, IL-18, TLR1, TLR2, and TLR3 are the predominant DE genes after vvIBDV infection." (PMID 28086922, 2017). "The transcription of TLR1, TLR5 and TLR7 then rose again to a certain extent at the chronic stage of infection (T3)." (PMID 27661612, 2016). "Our results showed that F. hepatica infection significantly downregulated the mRNA expression of TLR1, TLR5, TLR6, TLR7 and TLR10 in PBMC at the acute stage of infection (T2)." (PMID 27661612, 2016). "Our results suggest that TLR1 and TLR6 mediate the innate immune response to M. haemolytica while TLR2 and TLR4 mediate response to infection by IBR and other viruses." (PMID 26121276, 2015). "TLRs are among the most important PRRs for the recognition of mycobacterial PAMPs during the early stages of infection, particularly the cell surface TLR2 (acting alone or as a heterodimeric complex with TLR1 or TLR6) and TLR4 receptors." (PMID 22384131, 2012). "Regardless of the mechanism, maturation of DCs with ligands for TLRs such as TLR4 and TLR2/TLR1 increases DC-mediated HIV-1 capture and trans-infection of T cells." (PMID 20617179, 2010). "There was a low (<50 copies/per 104 β-actin), but significant upregulation of TLR-1 and TLR-2 in SARS-CoV infected adult DCs at 3 h post infection." (PMID 19505311, 2009). "Notably, the bacterial ligand Pam3CSK4 (TLR1/2) and LPS (TLR4) specifically increased the infection levels in vaginal immature LCs." (PMID 36841916, 2023). "The results of the co-immunoprecipitation experiment showed TLR1 and TLR6 were better able to bind to a TLR2 primary antibody following infection with three strains of M. bovis compared with controls, which indicated that there was a crosstalk between TLR1/TLR2 and TLR2/TLR6." (PMID 35464378, 2022). "Previous studies showed that the expression of TLR1/3/7/8 were repressed strongly at 8 weeks post-infection during the course of Schistosoma infection, especially TLR3, and the expression of TLR1/2/4/9 were decreased on B cells and monocytes after filarial infection." (PMID 35739856, 2022). "These signaling pathways showed that, after LPS infection, several DEGs were mainly related to immune function, such as up-regulated expression of CCL5, IL8, NFKBIA, TRAF3, and TNFAIP3, and down-regulated expression of MEF2C, MAP2K6, TLR1, TLR2, and IRF5." (PMID 34067819, 2021). "Compared to TLR1/2 signaling and pyruvate catabolic pathways, caspase-1-induced pyroptosis did not play a major role in our infection model." (PMID 34933448, 2021). "The lack of differential expression of other TLR genes in this study is in contrast to a previous study of transcriptomic response of ovine PBMC conducted by our group, where TLR1, TLR5, TLR6, TLR7 and TLR10 were downregulated in PBMC at the acute stage of infection." (PMID 34616397, 2021).